NDUFA5 (NADH:ubiquinone oxidoreductase subunit A5)
Description:
Accessory subunit of the mitochondrial membrane respiratory chain NADH dehydrogenase (Complex I), that is believed not to be involved in catalysis. Complex I functions in the transfer of electrons from NADH to the respiratory chain. The immediate electron acceptor for the enzyme is believed to be ubiquinone.
Synonyms: CI-13kD-B; B13; NUFM; UQOR13; CI-13kB
Tractability: Small molecule: an approved drug acts on it; a structure with a bound ligand is known. Antibody: UniProt places it where antibodies can reach, with high confidence. PROTAC: its protein half-life has been measured.
Target class: Enzyme; Oxidoreductase
Gene: Protein-coding gene on chromosome 7 (123,536,997 to 123,557,904, reverse strand). Ensembl gene ENSG00000128609.
Subcellular location: Mitochondrion inner membrane
Subcellular location (Human Protein Atlas): Mitochondria
Pathways (Reactome):
Metabolism: Complex I biogenesis; Respiratory electron transport
Signal Transduction: RHOG GTPase cycle
Gene Ontology:
Molecular function: protein binding; NADH dehydrogenase (ubiquinone) activity
Biological process: aerobic respiration; mitochondrial electron transport, NADH to ubiquinone; proton motive force-driven mitochondrial ATP synthesis; respiratory electron transport chain; proton transmembrane transport
Cellular component: mitochondrial inner membrane; mitochondrion; respiratory chain complex I; protein-containing complex
Genetic constraint (gnomAD): Loss-of-function variants: 8 observed, 10.22 expected, observed/expected ratio (o/e) 0.78, 90% interval 0.46 to 1.41. The upper end of that interval is the gene's LOEUF score, 1.41, which puts it in group 5 of 6, group 1 being the genes least tolerant of losing a copy. Missense variants: 69 observed, 91.11 expected, observed/expected ratio (o/e) 0.76, 90% interval 0.62 to 0.93. Synonymous variants: 30 observed, 34.21 expected, observed/expected ratio (o/e) 0.88, 90% interval 0.65 to 1.19.
Homologues: Orthologues: chimpanzee NDUFA5 (100% identical), macaque NDUFA5 (95% identical), pig NDUFA5 (88% identical), guinea pig NDUFA5 (85% identical), mouse Ndufa5 (83% identical), rat Ndufa5 (80% identical), tropical clawed frog ndufa5 (72% identical), zebrafish ndufa5 (68% identical), Caenorhabditis elegans ndua-5 (53% identical), Drosophila melanogaster ND-13B (50% identical).
Diseases named in the same sentence as NDUFA5 in open-access papers:
NDUFA5 is named in the same sentence as 22 diseases in open-access papers, as found by Europe PMC text mining. Sharing a sentence is not in itself a finding about the gene and the disease. The quoted sentences say what the papers report.
Huntington disease (2 papers, 2013 to 2018). Huntington disease (HD) is a rare neurodegenerative disorder of the central nervous system characterized by unwanted choreatic movements, behavioral and psychiatric disturbances and dementia. "Some of the identified genes in this study, such as NDUFA5, are part of the canonical HD signaling pathway (KEGG pathway for Huntington’s disease), suggesting that alterations in genes commonly associated with HTT-mediated pathogenesis can be evaluated in peripheral blood." (PMID 23957861, 2013).
Parkinson disease (2 papers, 2018 to 2020). A progressive degenerative disorder of the central nervous system characterized by loss of dopamine producing neurons in the substantia nigra and the presence of Lewy bodies in the substantia nigra and locus coeruleus. "Neuronal complex I deficiency is not correlated with the neurodegeneration, mitochondrial DNA damage in Parkinson’s disease brain, nor in mice with a central nervous system knockout of Ndufa5." (PMID 32867129, 2020).
Cognitive impairment (1 paper, 2024). Abnormal cognition is characterized by deficits in thinking, reasoning, or remembering. "In participants with cognitive impairment, the expression levels of KEGG:M00146’s NDUFA2, NDUFA3, NDUFA4, NDUFA6, NDUFA7, NDUFA10, and NDUFA12 increased, but the expression levels of NDUFA5, NDUFA4L2, and NDUFAB1 marginally decreased." (PMID 38542318, 2024).
diabetes (1 paper, 2010). "NDUFA5, NDUFS7, SCO1 and FMO4 all are involved in oxidative phosphorylation and have been shown to be important in diabetes." (PMID 20122255, 2010).
fatty liver disease (1 paper, 2018). A reversible condition wherein large vacuoles of triglyceride fat accumulate in liver cells via the process of steatosis. "In conclusions, our findings supported that miR‐33a/NDUFA5 axis was an important mediator of hepatocyte mitochondrial function, and the therapeutic benefits implied miR‐33a antisense had the potential clinical application in combating fatty liver disease." (PMID 30324697, 2018). "Therefore, up‐regulation of hepatocyte NDUFA5 level might have benefits in preventing diet‐induced mitochondrial dysfunction and fatty liver disease." (PMID 30324697, 2018).
Leigh syndrome (1 paper, 2026). A progressive neurological disease defined by specific neuropathological features associating brainstem and basal ganglia lesions. "Our data demonstrate that bi-allelic variants in NDUFA5 cause a mitochondrial complex I deficiency, characterized by a variable multisystem phenotype that encompasses severe congenital heart defects, hematological abnormalities, and neurological involvement consistent with Leigh syndrome." (PMID 41916321, 2026).
tumor (6 papers, 2013 to 2022). "Some data allow suggesting that two subunits of Complex I of ETC of mitochondria, NDUFA4 and NDUFA5, determine its electron transport function and, thus, form the redox status of tumor that correlates with its metastatic potential which may have an important prognostic significance." (PMID 30581847, 2018). "Except for COXA5, expression of NDUFA5 and UQCRB were either constant (NDUAF5; P = 0.4934) or significantly reduced (UQCRB; P < 0.0001) in HCC when compared to adjacent non-tumor tissue in the GSE36376 cohort." (PMID 30430110, 2018). "Subsequently, we confirmed well-characterized oncogenes among tumor-related loci (such as EGFR and KIT) and detected novel genes that gained chromosome sequences (such as AASS, HYAL4, NDUFA5 and SPAM1) in both LGG and HGG." (PMID 23451178, 2013).
NDUFA5 also shares sentences with these, for which no sentence is quoted: infection (3 papers); Alzheimer disease (2); COVID-19 (2); ovarian carcinoma (2); autism (1); autism spectrum disorder (1); cancer (1); cardiac hypertrophy (1); melanoma (1); neurodegenerative disease (1); non-alcoholic fatty liver disease (1); osteoporosis (1); squamous cell carcinoma (1); steatosis (1); type-2 diabetes (1).